LY6G5C (lymphocyte antigen 6 family member G5C)
Description:
May have a role in hematopoietic cell differentiation.
Synonyms: C6orf20; G5C; NG33; LY6G5CA; LY6G5CB
Tractability: Antibody: UniProt places it where antibodies can reach, with high confidence; UniProt predicts a signal peptide or a membrane-spanning region; its Gene Ontology location is reachable by antibodies, with medium confidence.
Gene: Protein-coding gene on chromosome 6 (31,676,684 to 31,684,040, reverse strand). Ensembl gene ENSG00000204428.
Subcellular location: Secreted
Gene Ontology:
Molecular function: identical protein binding
Cellular component: external side of plasma membrane; protein-containing complex; extracellular region
Genetic constraint (gnomAD): Loss-of-function variants: 6 observed, 11.21 expected, observed/expected ratio (o/e) 0.54, 90% interval 0.29 to 1.06. The upper end of that interval is the gene's LOEUF score, 1.06, which puts it in group 4 of 6, group 1 being the genes least tolerant of losing a copy. Missense variants: 160 observed, 190.82 expected, observed/expected ratio (o/e) 0.84, 90% interval 0.74 to 0.96. Synonymous variants: 69 observed, 71.19 expected, observed/expected ratio (o/e) 0.97, 90% interval 0.8 to 1.18.
Homologues: Orthologues: chimpanzee LY6G5C (97% identical), macaque LY6G5C (85% identical), mouse Ly6g5c (67% identical), pig LY6G5C (64% identical), rat Ly6g5c (63% identical), dog LY6G5C (61% identical), rabbit LY6G5C (61% identical), guinea pig LY6G5C (59% identical).
Diseases named in the same sentence as LY6G5C in open-access papers:
LY6G5C is named in the same sentence as 4 diseases in open-access papers, as found by Europe PMC text mining. Sharing a sentence is not in itself a finding about the gene and the disease. The quoted sentences say what the papers report.
cognitive decline (1 paper, 2021). "Furthermore, DMRs annotated to MORN4, AIRE, LY6G5C, and PRRT1 were identified for both rates of cognitive decline as measured by the slopes of mPACCdigit/mPACCtrailsB and CDR-SB." (PMID 34654479, 2021).
gastric cancer (1 paper, 2015). A primary or metastatic malignant neoplasm involving the stomach. "Aberrant methylation at the genes B3GATL4 (6p21.3), TNXB (6p21.3), TRIM31 (6p21.3), LY6G5C (6p21.33), KIAA1949/PPP1R18 (6p21.3), and GNL1 (6p21.3) identified in NPC was also hypermethylated in EBV-positive gastric cancers compared to EBV-negative gastric cancers (FDR < 1.6 × 10−90)." (PMID 25924914, 2015).
cancer (1 paper, 2025). A tumor composed of atypical neoplastic, often pleomorphic cells that invade other tissues. "LY6G5C, next on the list, is a lymphocyte antigen-6 family member, whose other loci have been investigated for their roles in cancer cells' survival from the immune system." (PMID 39897058, 2025).
tumor (1 paper, 2023). "Interestingly, some of the common down-regulated genes, such as EPHA7 and NSUN7, are known for both their tumor suppressing and promoting roles, or are associated with overall survival (OS) (SLC22A31), while others have clear pro-tumorigenic roles (ADGRF1, LOX, LY6G5C, SNAI2, TNFRSF11B, ZNF233)." (PMID 36769365, 2023).